RNU6-1136P (RNA, U6 small nuclear 1136, pseudogene)
Gene: Small nuclear RNA gene on chromosome 7 (102,834,605 to 102,834,708, forward strand). Ensembl gene ENSG00000252643.
Homologues: Orthologues: chimpanzee U6 (97% identical), macaque U6 (92% identical), pig U6 (76% identical). Paralogues in human: RNU6-959P (86% identical), RNU6-1011P (85% identical), RNU6-1060P (85% identical), RNU6-1103P (85% identical), RNU6-1122P (85% identical), RNU6-1158P (85% identical), RNU6-15P (85% identical), RNU6-38P (85% identical), RNU6-455P (85% identical), RNU6-476P (85% identical), RNU6-116P (84% identical), RNU6-1263P (84% identical), and 1286 more.